PTPN11 (protein tyrosine phosphatase non-receptor type 11)
Diseases named in the same sentence as PTPN11 in open-access papers (continued):
Sharing a sentence is not in itself a finding about the gene and the disease.
Alzheimer disease (4 papers, 2022 to 2025). A progressive, neurodegenerative disease characterized by loss of function and death of nerve cells in several areas of the brain leading to loss of cognitive function such as memory and language. "Particularly, TREML-1 can enhance the calcium signalling in an SHP2 (PTPN11)-dependent manner, whereas some genetic variant of TREML-2 have been identified to be protective for Alzheimer’s disease, contrary to TREM-2 genetic variants." (PMID 40948752, 2025). "PTPN11 (also known as SHP2) interacts with tau in Alzheimer's disease brain." (PMID 37520124, 2023). "We also identified genes such as PTPN11 (also known as protein tyrosine phosphatase SHP2), and MCM2, involved in cell maintenance and renewal, which have been characterized as risk factors for Alzheimer’s Disease." (PMID 39086978, 2022).
asthma (4 papers, 2016 to 2024). "Both PTPN11 p.R173L and LZTR1 p.R170Q carriers had been diagnosed with asthma." (PMID 38654924, 2024).
bladder cancer (4 papers, 2016 to 2023). "Both inhibition and overexpression of miR-301b were confirmed to regulate PTPN11 protein expression, suggesting PTPN11 as a direct target gene of miR-301b in bladder cancer." (PMID 26837847, 2016). "Collectively, the miR-130 family might modulate cellular signaling pathways of bladder cancer cells by regulating various target genes, including PTEN and PTPN11." (PMID 26837847, 2016). "Therefore, the upregulation of EP300, PTPN11, and RAC1 genes may play a role in the development of NDV persistent infection in EJ28 bladder cancer cell line." (PMID 37147328, 2023).
colon adenocarcinoma (4 papers, 2019 to 2023). "Moreover, only one meta-analysis showed that coffee polyphenols, caffeic acid and chlorogenic acid increased the MYO9B, PTPN11 and CDH1 gene expressions in un-stimulated colon adenocarcinoma HT29 cells." (PMID 33806347, 2021).
Down syndrome (4 papers, 2017 to 2025). "Our paradigmatic case (Case 1), apart from reporting the ALL vs. JMML sequence closely related to the PTPN11 germline alteration, showed the rarely described presentation of a TMD at birth, as is common in Down syndrome." (PMID 39336782, 2024).
heart failure (4 papers, 2019 to 2025). Inability of the heart to pump blood at an adequate rate to meet tissue metabolic requirements. "Three patients with a mutation in exon 13 of the PTPN11 gene died of cardiac failure at the ages of 3.0, 3.5, and 6.0 months." (PMID 30732632, 2019). "This case is significant as it emphasizes the importance of recognizing the various cardiac manifestations in NSML, especially in patients with exon 12 of the PTPN11 mutation, and highlights the need to consider differential diagnoses in heart failure patients with distinctive facial features." (PMID 39898109, 2025). "Three patients with a mutation in exon 13 of the PTPN11 gene had rapidly progressive HCM and died of cardiac failure at the age of 3.0, 3.5, and 6.0 months, respectively." (PMID 30732632, 2019).
ischemic heart disease (4 papers, 2011 to 2023). "Protein tyrosine phosphatase nonreceptor type 11 corresponding PTPN11 mutation induces diffuse bilateral dilatation of the coronary arteries and influences vascular fragility in the coronary artery, even if the patient shows no symptoms of ischemic heart disease." (PMID 34012683, 2021).
liver fibrosis (4 papers, 2022 to 2024). "The literature also shows that PTPN11 inhibitors can alleviate CCl4-induced liver fibrosis, but transcriptome data show that tanshinone IIA can upregulate PTPN11." (PMID 35517817, 2022).
male infertility (4 papers, 2015 to 2024). The inability of the male to effect fertilization of an ovum after a specified period of unprotected intercourse. "Naturally occurring mutations in PTPN11 caused genetic disorders characterized by a spectrum of defects, including male infertility." (PMID 38001535, 2023).
Osteopenia (4 papers, 2017 to 2025). Osteopenia is a term to define bone density that is not normal but also not as low as osteoporosis. "CD109 was also associated with mature OBs, and PTPN11 KO mice exhibited osteopenia phenotypes." (PMID 36181557, 2022).
allergic reaction (3 papers, 2012 to 2025). "GWAS data further strengthen the link between these genes and diseases, with BATF, CEBPA, and ETS1 associated with allergic diseases, and PTPN22, ETS1, PTPN11, and BATF linked to RA." (PMID 40839671, 2025).
astrocytoma (3 papers, 2022 to 2025). "The astrocytoma tissue showed a higher PTPN11 variant allele frequency." (PMID 35778969, 2022).
dilated cardiomyopathy (3 papers, 2014 to 2022). Cardiomyopathy which is characterized by dilation and contractile dysfunction of the left and right ventricles. "For example, mice with a Ptpn11 deletion in the cardiomyocytes show that Shp2 is required for the suppression of dilated cardiomyopathy." (PMID 24736444, 2014).
glioneuronal tumor (3 papers, 2019 to 2026). "CONCLUSION: PTPN11-related NS predisposes to multifocal low-grade glial and glioneuronal tumors confirmed by radiological, histological, and molecular characteristics." (PMID 41784910, 2026).
hydrops (3 papers, 2019 to 2023). "PTPN11 variants (all missense, one de novo, two inherited) were found in fetuses with multisystem anomalies, hydrops, and increased nuchal translucency phenotypes." (PMID 30712880, 2019).
infiltrating ductal carcinoma (3 papers, 2012 to 2025). "PTPN11 upregulation has been noted in infiltrating ductal carcinomas, its activity has been implicated in integrin signaling during in vitro migration through Matrigel, and a recent report suggests a function for PTPN11 in tumor-initiating cells maintenance." (PMID 23113900, 2012).
left ventricular hypertrophy (3 papers, 2017 to 2024). Enlargement of the LEFT VENTRICLE of the heart. "Finally, earlier versions of the Blueprint Genetics HCM panel did not include the now well-established HCM/left ventricular hypertrophy genes PLN and PTPN11, which might also have an impact on overall yield." (PMID 33673806, 2021).
lipodystrophy (3 papers, 2013 to 2023). A congenital or acquired disorder characterized by abnormal loss or redistribution of the adipose tissue in the body. "ACOX1, ALDOB, protein kinase AMP-activated catalytic subunit alpha 2 (PRKAA2), JAK3, and protein tyrosine phosphatase non-receptor type 11 (PTPN11) have been confirmed to be closely related to β-oxidation of fatty acid, lipogenesis, cholesterol metabolism, and lipodystrophy." (PMID 36397714, 2023).
myopia (3 papers, 2018 to 2019). "High refractive errors, defined as 5 diopters or more, were found for myopia in 5 patients, for hyperopia in 2 patients, and for astigmatism in 3 patients, mainly associated with a causative PTPN11 mutation." (PMID 29948256, 2018).
neurofibroma (3 papers, 2022 to 2025). An intraneural or extraneural neoplasm arising from nerve tissues and neural sheaths. "This represents a unique case manifesting as orbital and lumbosacral plexiform neurofibromas carrying a PTPN11 gene mutation, thereby broadening the phenotype spectrum of PTPN11 mutations." (PMID 39006611, 2024).
non-alcoholic steatohepatitis (3 papers, 2023 to 2025). "PTPN11 in hepatocytes could induce early-onset non-alcoholic steatohepatitis (NASH)." (PMID 36866057, 2023).
Parkinson disease (3 papers, 2017 to 2025). A progressive degenerative disorder of the central nervous system characterized by loss of dopamine producing neurons in the substantia nigra and the presence of Lewy bodies in the substantia nigra and locus coeruleus. "By enrichment analysis, PTPN11 was found to be significantly enriched in pathways such as ribosome, OXPHOS, and Parkinson’s disease." (PMID 41367010, 2025).
rectum adenocarcinoma (3 papers, 2022 to 2025). An adenocarcinoma arising from the rectum. "However, higher expression of PTPN11 was related to longer OS in cases with ESCA (p = 0.0016), KIRC (p < 0.001), rectum adenocarcinoma (READ) (p = 0.017), and THYM (p = 0.029)." (PMID 35802774, 2022).
Usher syndrome (3 papers, 2022 to 2023). A syndromic diseae characterized by the association of sensorineural deafness (usually congenital) with retinitis pigmentosa and progressive vision loss. "Unlike CDH23 and PDZD7, which cause non-syndromic hearing loss or Usher syndrome presenting as non-syndromic hearing loss during childhood, PTPN11 is associated with NS1, which shows a variety of phenotypes in multiple organs." (PMID 35248088, 2022).
anaplastic large cell lymphoma (2 papers, 2024). Anaplastic large cell lymphoma (ALCL) is a rare and aggressive peripheral T-cell non-Hodgkin lymphoma, belonging to the group of CD30-positive lymphoproliferative disorders, which affects lymph nodes and extranodal sites. "Upregulation of PTPN11 phosphatases have been reported to mediate resistance to ALK-TKI in ALK+ anaplastic large cell lymphoma and in a variety of other cancers." (PMID 39695132, 2024).
Arthritis (2 papers, 2012 to 2023). Inflammation of a joint. "The loss of SHP-2 (encoded by Ptpn11) in CD4-Cre;Ptpn11f/f mice resulted in the induction of AS-like pathological characteristics, including spontaneous cartilage and bone lesions, kyphosis, and arthritis." (PMID 37048045, 2023).
auditory neuropathy (2 papers, 2021 to 2022). A hearing disorder characterized by impaired transmission of signals through the auditory nerve, resulting in mild to severe hearing loss and poor speech perception. "Similarly, protein tyrosine phosphatase non-receptor type 1 (PTPN11) c.1001T>A was prioritized by EVIDENCE, but this was incompatible to the phenotype of auditory neuropathy spectrum disorder (ANSD) in SB422-823." (PMID 34593925, 2021).
autoimmune thyroid disease (2 papers, 2020 to 2024). Inflammatory disease of the thyroid gland due to autoimmune responses leading to lymphocytic infiltration of the gland. "Those included autoimmune thyroiditis, SLE, polyendocrinopathy (association of autoimmune thyroiditis and CD), antiphospholipid syndrome, vitiligo, and autoimmune hepatitis and all occurred in patients with PTPN11 mutations." (PMID 32973676, 2020).
childhood cancers (2 papers, 2022 to 2024). "Similarly, patients with Noonan and Costello (OMIM 218040) syndromes, caused by the PTPN11 and HRAS genes, have higher risk of childhood cancers, facial dysmorphia, cardiac disorders, neurocognitive delays, and musculoskeletal and cardiac abnormalities." (PMID 38534435, 2024).
chordoma (2 papers, 2023 to 2024). Chordomas are rare malignant tumors arising from embryonic remnants of the notochord in axial skeleton. "SHP2 (encoded by PTPN11) is an oncogenic protein-tyrosine phosphatase that was found to be a genetic dependency for chordoma by genetic mapping using genome-scale CRISPR screening." (PMID 39696530, 2024). "Validating the therapeutic relevance of dependencies, small-molecule inhibitors of SHP2, encoded by PTPN11, have potent preclinical efficacy against chordoma." (PMID 37024492, 2023). "Several chordoma dependency genes identified in the primary screens, including PTPN11, EGFR, and CDK6, encode proteins that are currently targetable with small-molecule inhibitors." (PMID 37024492, 2023). "Our screens in chordoma similarly demonstrate dependency on both genes, but we noted that PTPN11 dependency scores are of a greater magnitude than those of EGFR." (PMID 37024492, 2023). "Genes were selected to represent both those functionally connected to other chordoma dependency genes (PTPN11, FANCM, ADAR, PRKRA, SOX9, SRRM2, SLC2A1, and SLC7A5), as well as those with putatively unique effects (LUC7L2 and CDK6)." (PMID 37024492, 2023). "Together, these findings using small-molecule perturbation of SHP2 further corroborate the essentiality of PTPN11 in various models of chordoma, and thus nominate SHP2 inhibitors as a therapeutic approach for the treatment of chordoma." (PMID 37024492, 2023).
coagulation defects (2 papers, 2019 to 2020). "Our findings are consistent with the literature, with a positive association between short stature, PS, coagulopathy, pectus deformities of the chest, and variants in PTPN11." (PMID 31057598, 2019).
COVID-19 (2 papers, 2020 to 2021). A disease caused by infection with severe acute respiratory syndrome coronavirus 2. "Thus, the parallel overexpression of RAC1 and PTPN11 in AD patients with COVID-19 could be important for the enhancing of neurotoxicity." (PMID 34948400, 2021). "Among our results, several immune-related pathways including those activated by Fc-epsilon-related signaling (LYN and PI3K), NIK/NF-κB (ub, CUL1, SKP1, proteasome, and NFKB2), and via C-type lectin receptor pathways (PTPN11 and CARD9) were enriched in the COVID-19 lungs." (PMID 33060566, 2020).
cystic hygroma (2 papers, 2016 to 2022). A benign lymphatic neoplasm usually arising from the neck and characterized by cystic dilation of the lymphatic vessels. "In the other, with a de novo likely pathogenic PTPN11 variant, post‐mortem confirmed the presence of a cystic hygroma." (PMID 34411415, 2022). "Mutations in the PTPN11 gene are associated with the autosomal dominant genetic disorder Noonan syndrome 1 (OMIM 163950), typically presenting with elevated NT and/or cystic hygroma in the 1st trimester ultrasound." (PMID 27168972, 2016).
eosinophilia (2 papers, 2023 to 2025). "This case highlights the formidable therapeutic challenges of FIP1L1-PDGFRA T674I-positive MPN with eosinophilia with concurrent PTPN11 (p.E76D) mutation." (PMID 40141849, 2025). "In this report, we present a case of a patient with FIP1L1-PDGFRA T674I-positive MPN with eosinophilia, harboring a PTPN11 (p.E76D) mutation." (PMID 40141849, 2025). "In the context of FIP1L1-PDGFRA-positive MPN with eosinophilia, the concurrent PTPN11 mutation could have amplified downstream signaling, making the leukemic cells less dependent on PDGFRA-driven pathways and more resistant to tyrosine kinase inhibitors like imatinib." (PMID 40141849, 2025). "This case presents the first reported instance of concurrent FIP1L1-PDGFRA T674I and PTPN11 (p.E76D) mutations in a 38-year-old male patient with MPN and eosinophilia." (PMID 40141849, 2025).
eosinophilic disorder (2 papers, 2025). "This case illustrates the therapeutic challenges associated with FIP1L1-PDGFRA T674I-positive eosinophilic disorder, especially when compounded by the PTPN11 mutation." (PMID 40141849, 2025). "This case highlights the complexities involved in treating FIP1L1-PDGFRA T674I-positive eosinophilic disorder, especially when compounded by additional mutations like PTPN11." (PMID 40141849, 2025). "The PTPN11 gene variations are suggested to promote eosinophilic disorders by leading to the activation of the RAS/MAPK pathway." (PMID 40514730, 2025).
epilepsy (2 papers, 2022 to 2023). A brain disorder characterized by episodes of abnormally increased neuronal discharge resulting in transient episodes of sensory or motor neurological dysfunction, or psychic dysfunction. "Exome-wide sequencing studies recently described PTPN11 as a novel brain somatic epilepsy gene." (PMID 36973520, 2023). "In the present study, we demonstrated that PTGS2, ESR1, MAPK1, PTPN11, and MAPK3 may be the targets of linoleic acid against epilepsy." (PMID 36034878, 2022).
growth disorders (2 papers, 2022 to 2023). "All these variants were identified in genes already associated with growth disorders: PROKR2 (N = 2), PTPN11 (N = 6), ANKRD11 (N = 1), NPR2 (N = 1), NF1 (N = 1), ACAN (N = 1), GH1 (N = 1), FBN1 (N = 1), COMP (N = 1), IGF1R (N = 1), ARID1A (N = 1), and CASR (N = 1)." (PMID 37605180, 2023).
hyperthyroidism (2 papers, 2018 to 2024). Overactivity of the thyroid gland resulting in overproduction of thyroid hormone and increased metabolic rate. "The relationship between hypothyroidism or hyperthyroidism and PTPN11 333–223A>G in univariable analysis did not hold in multivariable analysis (OR 0.4; 95% CI 0.2–1.0; p = 0.052)." (PMID 29695768, 2018).
hypothyroidism (2 papers, 2018 to 2020). Abnormally low levels of thyroid hormone. "For NS and RAS-opathy related phenotypes, variants in PTPN11 were associated with increased risk of hypothyroidism, high diastolic and systolic BP, and high standing/sitting height ratio." (PMID 33226994, 2020). "For example, rs11066309 in PTPN11 was significantly associated with a lower body mass index, an increased risk of hypothyroidism and a smaller size for gestational age, all in concordance with NS-related phenotypes." (PMID 33226994, 2020). "Similarly, the association between variants in PTPN11 and hypothyroidism as well as the association between JAG1 and birth weight were reported." (PMID 33226994, 2020). "At a gene level, PTPN11, NRAS, RASA2, SOS2, MAP2K1, and RAF1 were significantly associated with hypothyroidism, diastolic and systolic BP, birth weight, growth abnormality, subcutaneous adipose tissue, standing/sitting height ratio and body mass index." (PMID 33226994, 2020).
Legius syndrome (2 papers, 2019 to 2024). Legius syndrome, also known as NF1-like syndrome, is a rare, genetic skin pigmentation disorder characterized by multiple cafC)-au-lait macules with or without axillary or inguinal freckling. "Five of 10 findings were reported in the ClinVar database as LP/P variants linked to NS or Legius syndrome, including two well-established substitutions, PTPN11 p.N308D and p.M504V [Food and Drug Administration (FDA) expert panel: P]." (PMID 38654924, 2024).
lymphoid neoplasm (2 papers, 2022). A neoplasm composed of a lymphocytic cell population which is usually malignant (clonal) by molecular genetic and/or immunophenotypic analysis. "The results suggested expression levels of PTPN11 in lymphoid neoplasm diffuse large B-cell lymphoma (DLBC), brain lower-grade glioma (LGG), and thymoma (THYM) were significantly greater than that of corresponding normal tissues." (PMID 35802774, 2022).
meningioma (2 papers, 2023 to 2024). A generally slow growing tumor attached to the dura mater. "Variants typical for angiomatous (brain) meningioma are PIK3CA, KIT, PTPN11, CDH1, SMAD4, and SMARCB1; the variants typical for psammomatous meningioma are APC, FGFR2, HNF1A, STK11, and JAK3." (PMID 38476782, 2024). "There are no reports of a patient with NS with a PTPN11 mutation and a Grade 2 meningioma." (PMID 36882706, 2023).
metabolic syndrome (2 papers, 2022 to 2024). A cluster of metabolic risk factors for CARDIOVASCULAR DISEASES and TYPE 2 DIABETES MELLITUS. "First, PTPN11 has been identified as one of the potential candidates for metabolic syndrome in humans." (PMID 36140242, 2022).
Noonan-related syndrome (2 papers, 2022 to 2026). "One patient with NS/Noonan-related syndrome phenotype and SLE characteristics had been reported to have a PTPN11 mutation." (PMID 36275661, 2022).
Pectus excavatum (2 papers, 2013 to 2024). A defect of the chest wall characterized by a depression of the sternum, giving the chest ("pectus") a caved-in ("excavatum") appearance. "In this study, 63.2% of patients with a PTPN11 variant had pectus excavatum, and none of them underwent either surgical intervention or psychological assessment." (PMID 39596579, 2024).
prostate tumors (2 papers, 2019 to 2024). "PTEN-deficient prostate tumors similarly induce an immunosuppressive tumor microenvironment by upregulating PTPN11/SHP2 and inducing activity of the Jak2-Stat3 pathway." (PMID 30800125, 2019).